MET (MET proto-oncogene, receptor tyrosine kinase)
Diseases named in the same sentence as MET in open-access papers (continued):
Sharing a sentence is not in itself a finding about the gene and the disease.
cancer (continued). "c-MET signaling is hyperactivated in multiple cancers, due to MET mutations, amplification, or rearrangement." (PMID 35062949, 2022). "Overexpression of MET in cancer cells can make c-MET to be recognized as a tumor associated antigen (TAA) by CD8 cytotoxic T cells which can trigger immune system activation." (PMID 35081970, 2022). "In GC, the gain-of-function of MET is associated with promoting cancer cell survival, migration, and angiogenesis through MET amplification." (PMID 35884507, 2022). "PD-1 regulation of MET, which is an important proto-oncogene for many cancers, underlies how this axis supports PDAC progression." (PMID 35804822, 2022). "The HGF/c-MET pathway is essential in regulating multiple processes involved in tumorigenesis and multiple pathways associated with cancer and is a promising therapeutic target." (PMID 36482562, 2022). "This is especially true if EMT inhibitors activate the MET pathway, which has been linked to cancer metastasis." (PMID 36431766, 2022). "The binding of MET and its ligand causes the appearance of the characteristic hallmarks of cancer, including cell proliferation, inhibition of apoptosis, and invasion and metastasis, by activating downstream signaling pathways." (PMID 35755810, 2022). "Receptor tyrosine kinase MET overexpression is frequently observed in a range of different cancers, is associated with poor prognosis, and has been investigated in several clinical trials." (PMID 36035159, 2022). "We found that MET exon 14 skipping and MET amplification were significantly associated with cancer diagnosis at a late age." (PMID 35371328, 2022). "Tivantinib strongly inhibits MET autophosphorylation, causing cell growth arrest, and also prevents cancer cell proliferation, invasion, metastasis, and induces caspase-dependent apoptosis by blocking cascades of downstream signaling pathway." (PMID 35630066, 2022). "MET is a receptor tyrosine kinase encoded by the MET proto-oncogene that has a significant role in cancer cell progression." (PMID 35565287, 2022). "KRAS-mutated cancers are heterogeneous, and genomic commutations, MET amplification, metabolic reprogramming, and EGFR signaling represent some possible mechanisms of resistance to the KRASG12C inhibitors and immunotherapy." (PMID 36230855, 2022). "Based on this analysis, we identified significant differences in the expression of genes previously implicated in c-MET signaling, cell cycle regulation, and cancer-related processes." (PMID 35778602, 2022). "Another study demonstrated that XIST depletion leads to a decreased cancer cell proliferation associated with a reduction in MET protein levels through sponging miR-34a, which is able to inhibit MET protein synthesis." (PMID 35804851, 2022). "We also discovered a novel mechanism with regard to the regulatory function of THEMIS2 in enhancing MET activation phosphorylation to regulate cancer stemness by suppressing the association of PTP1B with p-MET." (PMID 34974522, 2022). "Although the high level of MET protein is associated with poor prognosis in cancer, it was less effective as a predictive biomarker for targeted therapeutic efficacy." (PMID 34974522, 2022). "MET overexpression has been found in various cancers in association with a poor prognosis and confers resistance not only to therapies targeting EGFR, BRAF, and MEK, but also to chemotherapies." (PMID 34207383, 2021). "Overexpression of MET is frequently observed in a range of different cancers and is associated with poor prognosis." (PMID 33526881, 2021). "A previous study about the variety of MET mutations in cancer used database analysis of 14,466 cancer cases and identified 186 cases with MET CN amplification." (PMID 33596971, 2021). "Overexpression of the receptor tyrosine kinase MET has been linked to poor survival in several cancer types, and MET has been suggested to interact with stem cell networks." (PMID 34069138, 2021).
cancer (continued). "Gene amplification of MET, which encodes for the receptor tyrosine kinase c-MET, occurs in a variety of human cancers." (PMID 33596971, 2021). "The cellular mesenchymal–epithelial transition (c-MET) signaling pathway has been reported to be associated with carcinogenesis, invasion, and metastasis in various cancers, including CRC." (PMID 34360807, 2021). "Although the MET gene undergoes many different types of mutation to become oncogenic, amplification of the MET locus has been reported in a variety of human cancers." (PMID 33596971, 2021). "The MET protein overexpression in cell is associated with the activation of multiple cancer-related pathways such as PI3K-Akt signaling pathway, FA, and central carbon metabolism in cancer pathways." (PMID 34262595, 2021). "The constitutive activation of this pathway can occur through amplification or mutation in the MET gene in several tumors to evade regulatory mechanisms of cancer formation." (PMID 34572947, 2021). "FAMC3 was amplified in strict association with MET amplification in several human cancers and cancer cell lines." (PMID 33596971, 2021). "The stimulation of surrounding cancer-associated fibroblasts (CAFs) increased production of HGF-sustained TKI resistance through the activation of MET-dependent signaling." (PMID 33804114, 2021). "Aberrant expression of MET and its ligand hepatocyte growth factor is associated with drug resistance in cancer therapy." (PMID 34761497, 2021). "We used MET exon 14 skipping as a case study for the detection of genetic variants in cancer driver genes through deep learning." (PMID 33921709, 2021). "Recurrent alterations at the same genomic site in cancer genes such as MET, MPL, FLT3, and KIT have been implicated in many different cancer types." (PMID 34068918, 2021). "MET is a proto-oncogene that encodes MET, and activating MET mutations have been reported in diverse carcinomas." (PMID 34677235, 2021). "RAC1 can also be activated by MET-associated complex in various cancer cells and promotes migration and invasion." (PMID 33204717, 2020). "The efficacy of chemotherapy-based liver cancer vaccination was markedly enhanced by targeting the MET–V-ATPase–MTOR axis, highlighting a translational strategy for identifying MET-associated drug candidates for cancer prevention." (PMID 32764535, 2020). "The expression of FLT4 and MET markers appeared to be associated predominantly with CK (+) cells, with the abundance of CK (+) EpCAM (-) phenotype being sharply elevated in cancer stage IA samples." (PMID 32899940, 2020). "Apart from two cases, N375S mutation (seven out of nine cases) did not co-exist with known driver alterations, further affirming the association of this MET variant with aggressive cancer phenotype." (PMID 32214092, 2020). "The aberrant activation of c-MET, such as that caused by gene amplification or mutations, is associated with many cancers." (PMID 32549194, 2020). "MET alterations (mutations, deletions and amplifications) have been found in various human cancers (cBioPortal)." (PMID 32030896, 2020). "The diversity of cancers in which MET mutations have been identified suggests that the MET protein, activated by mutations, plays an important role in the tumorigenic process in a wide range of cell types." (PMID 33375764, 2020). "c-MET receptors are activated in cancers through genomic events like tyrosine kinase domain mutations, juxtamembrane splicing mutation and amplified copy numbers, which can be inhibited by c-MET small molecule inhibitors." (PMID 32214092, 2020). "In agreement with this concept, the COSMIC (Catalogue of Somatic Mutations in Cancer) database lists six MET mutations affecting the MET caspase sites in various cancers." (PMID 32091387, 2020). "Decreased MIR22HG expression is associated with increased expression levels of MET and p21 oncogenes and cancer cell survival via its impact on YBX1 protein stability." (PMID 32760219, 2020).
cancer (continued). "Ligand-dependent MET activation is closely associated with the acquisition of resistance to anticancer drugs in the cancer microenvironment." (PMID 31212972, 2019). "On the other hand, amplification of c-MET was also associated with the escape of cancer cells from the anticancer effects of several targeted therapies." (PMID 31590382, 2019). "NPS-1034 is a newly developed dual AXL/MET inhibitor that exerts efficacy against cancer cells harbouring activated or mutated MET or AXL." (PMID 31684958, 2019). "In stage I-II pancreatic cancer, high MET expression was correlated with dismal prognosis and assisted in identifying patients with a high-risk of cancer recurrence and depressing survival prognoses." (PMID 31412643, 2019). "The MET RTK is often over-expressed in human cancers, and the activation of MET RTK is associated with aggressive cancer cell growth, metastasis and resistance towards a variety of anti-cancer drugs." (PMID 30760737, 2019). "Database analysis revealed that cancer cells carrying the resistance mutation in EGFR or MET amplification appear to depend on MTHFD2 for growth." (PMID 30532069, 2019). "cMet inhibitors are actively being studied in cancers bearing these mutations; a phase II clinical trial of tepotinib in NSCLC harboring MET exon 14 skipping alterations (NCT02864992) is underway." (PMID 31040125, 2019). "Over-expression of the MET receptor or its ligand HGF, MET amplification or gain-of-function mutation in MET are the various mechanisms for which MET pathway dysregulation is implicated in cancer development and progression." (PMID 29188469, 2018). "The activity of MET in cancer cells is also frequently increased due to the amplification of the MET gene or its activating mutations." (PMID 29719603, 2018). "In the network enrichment analysis, c‐MET has been identified as a hub which plays key roles in cancer initiation and progression of cigarette smoking‐associated NSCLC." (PMID 29570930, 2018). "MET, a member of the receptor tyrosine kinase family, is encoded by the Met gene on chromosome 7q31, has been found to be overexpressed in many cancers and some soft tissue tumors, including MFS." (PMID 30126419, 2018). "Deregulation of the receptor tyrosine kinase mesenchymal epithelial transition factor (MET) has been implicated in several human cancers and is an attractive target for small molecule drug discovery." (PMID 29949931, 2018). "MET is known to mediate resistance to various cancer therapies, and its over-expression in RCC associates with poor prognosis." (PMID 29389967, 2018). "CUP adenocarcinomas and poorly differentiated carcinomas harboured the highest frequency of variants in genes involved in signal transduction pathways (e.g. MET, EGFR, HRAS, KRAS, and BRAF)." (PMID 29973234, 2018). "The majority of these MET secondary mutations have been reported to be associated with crizotinib resistance in different cancers." (PMID 28460431, 2017). "Various types of cancers exhibit high levels of c-MET via gene amplification, overexpression, activating mutations, and increased autocrine or paracrine ligand-mediated stimulations." (PMID 29291022, 2017). "Next, to confirm the association of miR-206 with c-MET/EGFR in NRF2-silenced cancer cells, shNRF2-SKOV3 and shNRF2-A498 were transfected with the miR-206 inhibitor nucleotides." (PMID 29291022, 2017). "PIK3CA mutations can lead to resistance to MET inhibition, supporting future clinical evaluation of combinations of PI3K and MET inhibitors in common scenarios of malignant neoplasms featuring aberrant MET expression and PIK3CA mutations." (PMID 28532501, 2017). "MET mutations, MET amplifications or MET overexpression, which trigger ligand-independent activation of MET signaling, are rare in primary human cancer." (PMID 28420162, 2017). "HGF/SF-mediated activation of MET causes cell proliferation, cell migration, and angiogenesis, all of which contribute to cancer progression." (PMID 28827556, 2017).
cancer (continued). "More commonly HGF is produced by stromal cells, such as cancer-associated fibroblasts, and triggers MET activation in a paracrine fashion." (PMID 28420162, 2017). "Similar to our findings in RCC patients, MET overexpression was associated with multiple human cancers." (PMID 29104726, 2017). "Constitutive HGF/MET signaling is a hallmark of cancer cells and HGF and MET have both emerged as valid therapeutic targets." (PMID 28420162, 2017). "In this study we demonstrated that HGF, commonly produced by cancer-associated fibroblasts, confers resistance to MET kinase inhibitors in MET-amplified NSCLC cells." (PMID 28968967, 2017). "First, we focused on MET, an oncogene that plays a central role in pRCC, especially in the type I. We found rs11762213, a germline exonic single nucleotide polymorphism (SNP) inside MET, predicted cancer-specific survival (CSS) in type II pRCC." (PMID 28358873, 2017). "Since c-MET inhibitors are already in clinical development for the treatment of cancers of the lung, pancreas, or other organs in which KRAS mutations are also frequent, our findings suggest further interesting opportunities for combination therapy." (PMID 28807782, 2017). "Germline met proto-oncogene (MET) and fumarate hydratase (FH) alterations are the hallmark of these cancer syndromes, but are infrequent in sporadic cases." (PMID 27993170, 2016). "Over-expression and hyper-activation of MET has been found in various cancer types and is often associated with poor outcome, or a role in development and metastasis of cancer." (PMID 27105539, 2016). "Point mutations in the MST1R kinase gene can activate the MET gene in human cancers releasing the oncogenic and metastatic potential of the receptor." (PMID 29056725, 2016). "In cancer, the MET gene readily acquires mutations within diseased tissues, and more than 20 missense or activating mutations have been described." (PMID 27584154, 2016). "For example, MET gene mutation and amplification represent one of the major mechanisms causing constitutive active HGF/c-MET signaling in cancer cells." (PMID 27923392, 2016). "Cellular mesenchymal-epithelial transition factor (c-MET) is closely linked to human malignancies, which makes it an important target for treatment of cancer." (PMID 27187326, 2016). "Many studies reveal that HGF/c-MET axis is implicated in various human cancers, and genetic and epigenetic gain of functions of this signaling contributes to cancer development through a variety of mechanisms." (PMID 28536400, 2015). "In contrast to ccRCC18, relatively little is known about the mutations that drive pRCC growth and the clonality of copy number events and single-nucleotide variants (SNVs), apart from the small minority of cancers with changes in MET and FH." (PMID 25790038, 2015). "Accumulating evidence indicates that protein overexpression is one of the major mechanisms underlying the aberrant activation of MET, and overexpression of MET is associated with poor patient survival in a variety of types of cancer." (PMID 25965822, 2015). "We initially investigated all 31 cancers and paired constitutional DNA for mutations in the Mendelian pRCC genes MET, FH and FLCN." (PMID 25790038, 2015). "Collective biochemical and genetic evidence suggests an association between dysregulated HGF/MET signaling and selected human cancers." (PMID 28536405, 2015). "MET pathway is one of the most dysregulated pathways in human cancer with MET over-expression, amplification and/or mutations." (PMID 25294187, 2015). "HGF is the only known ligand for c-MET and c-MET has clearly been associated with aggressive disease, poor prognosis, worse clinical outcomes, and chemoresistance in many cancers." (PMID 26404380, 2015).
cancer (continued). "The induction of AXL or MET is associated with increased cellular mobility in cancers.We therefore investigated changes in cellular mobility in both the parental and gefitinib/erlotinib-resistant cells." (PMID 25780909, 2015). "Aberrant activation of the hepatocyte growth factor (HGF) receptor tyrosine kinase MET, mostly due to overexpression of the MET gene, is a common event in numerous types of human cancers and is frequently associated with poor prognosis." (PMID 26413215, 2015). "MET is a known oncogene that encodes a cell surface receptor tyrosine kinase, which is upregulated in a variety of human cancers." (PMID 25874496, 2015). "c-MET is aberrantly activated in many human cancers through diverse mechanisms, including point mutations, gene amplification, transcriptional up-regulation, or ligand autocrine loops." (PMID 26459369, 2015). "A total of 81 patients with advanced esophageal (n=36), GEJ (n=17) or gastric (n=28) cancers were evaluated for MET mutation/variant (41 patients) or amplification (76 patients)." (PMID 24742823, 2014). "Activation and/or overexpression of the MET oncoprotein generally was linked to poor prognosis in cancer patients, including breast carcinoma." (PMID 25230070, 2014). "MET encodes a tyrosine kinase receptor whose activation is involved in cancer progression. c-MET is physiologically activated by its natural ligand, hepatocyte growth factor (HGF)." (PMID 24742823, 2014). "The identification of a cancer type in which MET genetic alteration, mutation, or amplification is present in a significant subset such as OPSCC is of high interest." (PMID 24465403, 2014). "Cancer-associated c-MET activation triggers cell growth, survival, invasion, migration, and angiogenesis." (PMID 25098767, 2014). "The overexpression of the cell surface receptor Met tyrosine kinase MET is a hallmark of various types of cancers including pRCC and ccRCC." (PMID 24977165, 2014). "In contrast, MET mutation is responsible for familial renal carcinoma as well as for other sporadic types of cancers." (PMID 23296269, 2013). "Irradiation often enhances metastasis, particularly in cases of pancreatic carcinoma, and this is associated with the radiation-induced upregulation of MET in cancer cells." (PMID 23296269, 2013). "Membranous c-MET staining was observed in 2,655 (78.6%) of 3,378 successfully analyzed cancers and strong c-MET expression was significantly associated with a high Gleason grade (P=0.0018)." (PMID 23251249, 2013). "The newly discovered metastasis-associated in colon cancer-1 (MACC1) gene is a key regulator of the HGF/MET pathway." (PMID 22251819, 2012). "Studies have shown that c-MET is closely related to the cancer stem cell phonotype and is associated with SDF-1-CXCR4 and LIF-R-LIF axes for the trafficking of normal and malignant stem cells." (PMID 22253909, 2012). "These hits also provide ready targets such as the FGFR2, FGFR4, known oncogenes like MET, and the activin and ephrin receptors, that are likely to be linked to the oncogenic activation of the cancer tissues in which they are expressed." (PMID 23251904, 2012). "Metastasis-associated in colon cancer-1 (MACC1) is a newly identified gene that plays a role in colon cancer metastasis through upregulation of c-MET proto-oncogene (c-MET)." (PMID 21955323, 2011). "Human cancers are thought to initiate from a single mutated cell in the context of a normal organ, whereas in the c-MET mouse model, all liver cells overexpress the oncogene, potentially creating a different microenvironment for the pre-neoplastic cell." (PMID 21949730, 2011). "MET mutations also have different prognostic effects in the two cancer types." (PMID 41521799, 2026).